CD6 (CD6 molecule)
Diseases named in the same sentence as CD6 in open-access papers (continued):
Sharing a sentence is not in itself a finding about the gene and the disease.
tumor (32 papers, 2006 to 2026). "The interaction of CD318 and CD6 has been involved in the tumor microenvironment, mainly in suppressing the cytotoxic effect of T and NK cells." (PMID 40725832, 2025). "In vitro treatment with itolizumab, enhanced tumor cell lines killing by PBMCs, similar to that reported for other murine anti-human CD6 antibodies in different CD318+ tumor cell lines." (PMID 40391211, 2025). "While CD6 itself is primarily expressed on immune cells, its ligands are frequently expressed on tumor cells." (PMID 39996744, 2025). "Given that the STRING analysis revealed predicted interactions between tumor-associated CD318 and immune-related proteins such as CD6 and PRKCD, we further investigated the functional context of these associations using a Gene Ontology (GO) analysis." (PMID 40725832, 2025). "Biomimetic nanoparticle Cu2-xSe NPs was coated with CD6-expressing tumor cell membrane and formed CS-J@CM/6 NPs with the antidepressant Paxil (PX) after modification of tumor cell membrane surface." (PMID 40270890, 2025). "Higher loss of CD6 expression was observed in co-cultures with CD318+ tumor cell lines, compared with MCF-7 in the presence of isotype control pointing to a CD6 loss mechanism induced by CD6-CD318 association." (PMID 40391211, 2025). "Tumor cells overexpress most of the reported ligands for CD6, and their interaction plays an important role in tumor progression and invasion, as well as in tumoral immuno-evasive mechanism." (PMID 40391211, 2025). "Cell-cell interaction analysis demonstrated strong communication between CGR11-high tumor cells and immune components (TAMs, TECs, T cells) via ligand-receptor pairs such as CD6, CD46, MIF, VEGF, and TRAIL." (PMID 41573680, 2025). "In terms of specific communication signals, tumor-associated ductal cells increase the output of signals such as ALCAM and OCLN and the input of signals such as CD96 and CD6." (PMID 40688078, 2025). "Downmodulation of CD6 in co-cultures with CD318+ tumor cell lines was also observed in CD4 and CD8+ T cells, and NK cells (CD56+)." (PMID 40391211, 2025). "The biomimetic NPs are composed of ultrasmall Cu2−xSe NPs, JQ1, and tumor cell membrane modified with CD6, and are efficiently delivered into tumor through the specific interactions between CD6 and activated leukocyte cell adhesion molecule." (PMID 36698265, 2023). "Due to continuous antigen exposure (tumor), exhausted T cells gradually lose their effector function (CD8+ Teff), and CD6 is also down-regulated, decreasing its killing effect on tumor." (PMID 37213285, 2023). "All pre-clinical evidence available sustains promise for humoral and cellular anti-tumour strategies targeting CD6 against haematological and solid cancers, in its capacity to act as or mimic an immunomodulatory lymphocyte receptor." (PMID 38139340, 2023). "The present review will summarise recent reports on humoral and cellular anti-tumour strategies targeting CD6, a long known but less studied immunomodulatory lymphocyte receptor." (PMID 38139340, 2023). "Soon after CD318 was recognized as a second ligand of CD6, efforts were made to understand its potential role in anti-tumor immunity." (PMID 36275816, 2022). "Small HCC usually implies a better clinical outcome, and Cox hazards models based on GEPIA indicated that CD6 and MAPK10 were tumor suppressors associated with a good clinical prognosis, which was consistent with the results of our study." (PMID 33225985, 2020). "T cells (expressing Cd2, Cd3e, Cd3g, and Cd6) were the most abundant immune cell type in tumor tissues, followed by cytotoxic cells (expressing Gzma and Klrd1)." (PMID 32612611, 2020). "The activation of ALCAM (Activated Leukocyte Cell Adhesion Molecule) and CD6 signaling may suggest the enhancement of tumor cell adhesion and migration, which may help tumor cells infiltrate and metastasize to other tissues." (PMID 40932351, 2026).
tumor (continued). "Notably, we identified SLC26A3high tumor cells expressing ALCAM in close proximity to CD6+Tregs, suggesting potential involvement of ALCAM>>CD6 signaling in Treg recruitment." (PMID 40066698, 2025). "Specifically, APOE+ tumour cells were involved in the CD6‐driven network, along with immune cells." (PMID 39810624, 2025). "Targeting CD6 enhances lymphocyte-mediated anti-tumor immunity." (PMID 39996744, 2025). "CD6 downmodulation was observed in PBMCs co-cultured in vitro with tumor cell lines." (PMID 40391211, 2025). "As a highly differentiated M2-like TAMs subset, bM2-like TAMs may play an anti-tumor role by activating T cells via ALCAM/CD6 interactions, as well as by promoting α-SMA+ myofibroblasts production via TGF-β secretion." (PMID 39507421, 2024). "To explore if other key ALCAM-binding partners may contribute to the tumour-mesothelial interactions, we tested two well established partners, namely CD6 and L1CAM in all the cells used here." (PMID 36614319, 2023). "Nevertheless, in hIgG1-G396R carriers, there were increased proportions of IgG+ plasma cells, CXCR5+ T follicular helper cells, CD6+ tumor-resident memory T cells, and decreased proportions of LAYN+ exhausted T cells, implying that the variant favors the formation of an antitumor microenvironment." (PMID 35133976, 2022). "Finally, in the CD6 model, we noted that the primary tumor did not harbor the FAT2 variant (c.6838del) observed in the corresponding xenograft." (PMID 35326637, 2022). "Itolizumab, a humanized anti-CD6 antibody, enhanced the cytotoxic activity of CD8+ T cells and NK cells against CD318-expressing tumor cell lines." (PMID 40725832, 2025). "CD6 expression was measured on PBMCs treated with isotype control and challenged with CD318+ (MDA-MB-231 and NCI-H460) and CD318- (MCF-7) tumor cell lines." (PMID 40391211, 2025). "Particularly, the CD6–CD318 axis, where CD6, which is expressed on T and NK cells, interacts with CD318 expressed on tumor cells." (PMID 40725832, 2025). "In this process, the absence of CAF_CCL21 also impairs complement-dependent CR2 activation of B_CD74, while the dysfunction of B_CD74 weakens CD6-dependent activation of CD8+ T cells, thereby attenuating their involvement in anti-tumor immunity." (PMID 38505619, 2024). "In contrast to the unconjugated mAb, the antibody-drug conjugate (CD6-ADC) selectively killed TCL cells in vitro and, more importantly, its systemic or local administration significantly reduced established TCL tumours in immunodeficient NSG mice." (PMID 38139340, 2023). "This would not only result from CD6 expression by T (TCL) and B (CLL) lymphoid malignancies, but also from the functional relevance of CD6–ligand interactions in anti-tumour immune responses and tumorigenesis." (PMID 38139340, 2023). "PTCL is diagnosed when tumor cells express the mature T cell antigens CD2, CD3, CD4, CD5, CD6, or CD7 on immunohistochemical staining." (PMID 21310044, 2011). "In the present work, improved tumor cell killing by itolizumab-treated PBMCs was not dependent on the blockade of CD6-ALCAM interaction." (PMID 40391211, 2025). "The present work shows an immunosuppressive effect of CD318 but not ALCAM on tumor cells, hampering proliferative responses of T cells and reducing immune cell viability and frequencies of CD6+ lymphocytes on co-cultures." (PMID 40391211, 2025). "Increased cancer killing was not induced by ADCC or complement-dependent cytotoxicity (CDC) as none of the tumor lines tested were CD6 positive, and itolizumab was proven not to induce ADCC or CDC." (PMID 40391211, 2025). "In line with previous studies using non-depleting anti-human and mouse CD6 mAbs, available evidence argues against the possibility that shCD6-based anti-tumour strategies would instigate the development of autoimmune side effects." (PMID 38139340, 2023).
tumor (continued). "CD6 expression was not altered on immune cells (CD45+) co-cultured with MDA-MB-231 lines in the transwell system, suggesting that CD6 downmodulation is caused by the direct interaction of PBMC and tumor lines and not by the presence of soluble forms of CD318." (PMID 40391211, 2025). "Furthermore, CD6 activation of T cells promotes TCR diversity 59, while CR2-mediated complement pathway activation enhances B cell-driven activation of tumor-specific CD8+ T cells in anti-tumor immunity." (PMID 38505619, 2024). "Interestingly, although itolizumab-treated PBMCs co-cultured with tumor cell lines show similar CD6 downmodulation, the functional responses are different in each condition, suggesting that CD318 and itolizumab decrease CD6 expression by a different mechanism that could trigger alternative outcomes." (PMID 40391211, 2025). "Unlike what was observed for CD6, confronting PBMCs with tumor cell lines does not modify CD5 expression on immune cells, which suggests that despite its high structural homology with CD6, neither CD318 nor ALCAM had an impact on CD5 expression." (PMID 40391211, 2025). "The downmodulation of CD6 and CD5 by itolizumab independent of CD318 expression suggests a regulatory mechanism of anti-tumor responses." (PMID 40391211, 2025). "The six critical genes, including CCR7, FCGR2B, BTLA, CD6, CD3D and CD3E, play important roles in favoring tumor progression and promoting negative immune-regulatory effects." (PMID 36291815, 2022). "APOE− tumor cells may promote tumor growth by interacting with dendritic cells and CD4+ T cells via CD99‐ rather than CD6‐regulated signaling." (PMID 39810624, 2025).
cancer (27 papers, 2020 to 2026). A tumor composed of atypical neoplastic, often pleomorphic cells that invade other tissues. "CD6 serves as a therapeutic target in cancer immunotherapy, while CD40 is associated with the severity of COPD and the degree of pulmonary function alteration." (PMID 39206312, 2024). "Despite CD318 being expressed in normal tissues, several findings suggest that toxicities associated with inhibition of its interactions with CD6 in patients with cancer, will be clinically manageable." (PMID 36275816, 2022). "Based on the small number of data associating CD5 and CD6 with cancer, we cannot draw a clear conclusion and thus a question remains in mind: are they a potential link between PD and cancer?" (PMID 35055157, 2022). "Certainly, the role of CD5 and CD6 in PD-associated cancers should be furtherly investigated." (PMID 35055157, 2022). "The previous finding that CD6 is expressed by T‐lymphocytes and NK cells to increase cancer cell death supports our newly identified gene signature." (PMID 41541656, 2026). "The soluble form of extracellular domains of CD6 has been successfully used in different mouse cancer models." (PMID 40391211, 2025). "As a humanized antibody, itolizumab offers a clinically safer relevant therapeutic scenario for cancer treatment over other murine anti-CD6 antibodies." (PMID 40391211, 2025). "CD6 plays critical roles in lymphocyte activation, proliferation, and adhesion to antigen-presenting, epithelial, and cancer cells." (PMID 39996744, 2025). "In light of these findings, current research is investigating how the interruption of CD6 interactions with its ligands can be utilized as a novel immunotherapy for cancer." (PMID 39996744, 2025). "Altogether, these results provide mechanistic support for anti-CD6 therapy as a promising mAb for cancer immunotherapy." (PMID 38280067, 2024). "Instead, binding and internalization of UMCD6 and cell surface CD6 directly alters the program of gene expression in lymphocytes, while controlling the effects of signals from CD6 ligands on cancer cells." (PMID 38280067, 2024). "Investigations have been conducted to assess the impact of the anti-CD6 monoclonal antibody UMCD6 on the cytotoxicity of human lymphocytes against cancer cells." (PMID 38225277, 2024). "The proteolytic cleavage of the CD6 extracellular region following lymphocyte activation gives rise to soluble CD6 (sCD6), which is found in serum of cancer patients." (PMID 39840036, 2024). "The interaction between galectins and CD6 is thus highly relevant as a potential therapeutic target in various diseases, including cancer." (PMID 39840036, 2024). "recent studies strongly suggest that anti-CD6 should also be evaluated as a new cancer immunotherapy." (PMID 39175079, 2024). "The multifaceted properties of CD6 make this receptor an exciting candidate for its use as an alternative and adjunctive immunotherapy in cancer." (PMID 38139340, 2023). "Of particular interest was the finding that CD6-CAR T cells also showed potent cytotoxic responses against human CRC cancer stem cells, which exhibit robust CD166/ALCAM expression." (PMID 38139340, 2023). "In recent years, the CD6-ALCAM axis has been implicated in the pathogenesis of multiple autoimmune diseases and cancer." (PMID 36275816, 2022). "CD6 interacts with its ligands on cancer cells restricting adaptive and innate antitumor immune responses." (PMID 36291815, 2022). "All lines tested expressed moderate to high levels of CD166/ALCAM, a ligand of CD6 that is found on activated leukocytes, cancer cells, and many normal tissue cell populations." (PMID 33497367, 2021). "The data in this report establish that the anti-CD6 mAb UMCD6 powerfully stimulates the ability of human lymphocytes to kill cancer cells of multiple types." (PMID 33497367, 2021).
cancer (continued). "The dual capability of anti-CD6 monoclonal antibody to enhance killing of cancer cells through its effects on both CD8+ T cells and NK cells opens a new avenue for cancer immunotherapy." (PMID 34071188, 2021). "The ability of CD6 to modulate important physiological lymphocyte processes warrants exploration of its immunomodulatory potential in cancer therapy." (PMID 33287301, 2020). "CD6 targeting is an interesting candidate for alternative or complementary cancer immunotherapies." (PMID 40391211, 2025). "It is remains to be proven whether the use of different anti‐CD6 Mab, despite their specific characteristics, will lead to the same outcome in cancer immunotherapy." (PMID 40391211, 2025). "Although much remains unknown about the interactions of CD6 with its ligands, the data from experimental systems argues for testing anti-CD6 as a novel, lymphocyte-engaging cancer immunotherapy in human cancer patients." (PMID 39840036, 2024). "Therefore, there has been an increased focus on understanding how CD6 interacts with its ligands in the context of cancer biology and cancer immunotherapy." (PMID 39840036, 2024). "Considering that many cancers simultaneously express CD166 and CD318, which bind to different epitopes of CD6, the functional consequences of CD6-mediated interactions between cancer cells and lymphocytes may be a blend of distinct signals from each ligand." (PMID 39840036, 2024). "Perhaps more importantly is the fact that these CD6-CAR-T cells exhibited strong cytotoxicity against CRC cancer stem cells, indicating that CD6-CAR-T might be a promising treatment strategy for CRC." (PMID 39840036, 2024). "Interestingly, CD6 is exclusively expressed on immune cells while CD318 is strongly expressed on most cancers." (PMID 37886483, 2023). "Currently, there are bidirectional roles of CD5 and CD6 in cancer immunity." (PMID 35983088, 2022). "Interestingly, the study based on mouse models reported that the absence or blockade of CD5- and CD6-mediated signals resulted in the dysfunction of the immune response, subsequently enhancing cancer progression." (PMID 35055157, 2022). "CD5 and CD6 molecules play a role in cancer and chronic lymphocytic leukemia." (PMID 35055157, 2022). "CD5 and CD6 have been demonstrated to affect the immune response to cancers." (PMID 35983088, 2022). "The hypothesis that cancer cell ligands of CD6 impair the function of cytotoxic lymphocytes is supported by experiments in which forced expression in vivo of a soluble form of CD6 was successfully employed as an anticancer strategy in mice." (PMID 33497367, 2021). "We investigated whether blocking CD6 or CD318 would affect immune cell–mediated killing of multiple cancer cell lines and overall growth/survival of the cultured cancer cells." (PMID 33497367, 2021). "The known relevance of CD6-CD166/ALCAM interaction in cell-to-cell adhesive contacts established between T cells and other immune (B cells, macrophages, dendritic cells) and non-immune (endothelial, epithelial) cells warrants future studies of CD6 variation in cancer." (PMID 34070159, 2021). "Additionally, CD6 is a potential target for cancer immunotherapy." (PMID 39996744, 2025). "Therefore, evidence that the first‐in‐class humanized anti‐human CD6 antibody itolizumab could be used for cancer immunotherapy may be a breakthrough in developing an antitumor clinical approach." (PMID 40391211, 2025). "However, the relationship between galectins and CD6 could be significant for developing new treatments for diseases, especially cancer." (PMID 39996744, 2025). "Consequently, CD6 emerges as a prospective target for cancer immunotherapy." (PMID 38225277, 2024). "Following an FDA-approved approach to cancer treatment, we developed a CD6-ADC by conjugating an MMAE onto a high-affinity anti-human CD6 mAb." (PMID 37917882, 2023). "Anti-CD318 produces a more modest effect on cancer cell death and survival compared to UMCD6 (anti-CD6)." (PMID 36275816, 2022).
cancer (continued). "A recent study suggested that the anti-CD6 monoclonal antibody, UMCD6, enhanced killing of cancer cells through effects on NK and CD8+ cells." (PMID 36482940, 2022). "Multiple human cancer cell lines were analyzed by flow cytometry for expression of CD318, which was recently described as a second ligand of CD6." (PMID 33497367, 2021). "CD6, CCL19, CD40LG, XCR1, MAGEA1, ATM and CCL19 genes were significantly differentially expressed in MET-altered cancers." (PMID 33437521, 2020). "CD44, a new ligand for CD6, is also expressed on cancer cells as well as many non-malignant cell types." (PMID 39996744, 2025). "In co-culture experiments with cell lines derived from human triple-negative breast cancer, non-small-cell lung cancer, and prostate cancer, substantial enhancement of cancer cell death and reduced survival of cancer cells was found in the presence of human lymphocytes and UMCD6 (anti-CD6)." (PMID 36275816, 2022). "The heightened ability of UMCD6-treated CD6– lymphocytes to kill cancer cells implies that CD6 ligands on the cancer cells deliver a negative signal to CD8+ and NK cytotoxic lymphocytes." (PMID 33497367, 2021). "Indeed, the present study has shown that all four cancer cell lines and the mesothelial cells are largely negative for CD6 and L1CAM." (PMID 36614319, 2023). "Interpretation of the effects of anti-CD318 could be confounded by the potential for nonspecific triggering of antibody-dependent cellular cytotoxicity through opsonization of cancer cells by anti-CD318, in addition to interruption of the ability of CD318 to engage CD6." (PMID 33497367, 2021).